MCM3AP (minichromosome maintenance complex component 3 associated protein)
Description:
[Isoform GANP]: As a component of the TREX-2 complex, involved in the export of mRNAs to the cytoplasm through the nuclear pores. Through the acetylation of histones, affects the assembly of nucleosomes at immunoglobulin variable region genes and promotes the recruitment and positioning of transcription complex to favor DNA cytosine deaminase AICDA/AID targeting, hence promoting somatic hypermutations. [Isoform MCM3AP]: Binds to and acetylates the replication protein MCM3. Plays a role in the initiation of DNA replication and participates in controls that ensure that DNA replication initiates only once per cell cycle. Through the acetylation of histones, affects the assembly of nucleosomes at immunoglobulin variable region genes and promotes the recruitment and positioning of transcription complex to favor DNA cytosine deaminase AICDA/AID targeting, hence promoting somatic hypermutations.
Synonyms: GANP; KIAA0572; MAP80; SAC3; PNRIID
Tractability: PROTAC: ubiquitination databases record sites on it; its protein half-life has been measured.
Gene: Protein-coding gene on chromosome 21 (46,235,133 to 46,286,297, reverse strand). Ensembl gene ENSG00000160294.
Subcellular location: Nucleus envelope (Isoform GANP); Nucleus, nuclear pore complex; Nucleus, nucleoplasm; Chromosome; Cytoplasm (Isoform MCM3AP); Nucleus
Subcellular location (Human Protein Atlas): Cytosol; Nuclear membrane; Nucleoplasm
Gene Ontology:
Molecular function: chromatin binding; histone acetyltransferase activity; histone binding; histone H3 acetyltransferase activity; protein binding; nucleic acid binding; protein-lysine-acetyltransferase activity
Biological process: nucleosome organization; poly(A)+ mRNA export from nucleus; somatic hypermutation of immunoglobulin genes; mRNA export from nucleus; positive regulation of transcription by RNA polymerase II
Cellular component: chromosome; cytoplasm; cytosol; nuclear envelope; nuclear membrane; nuclear pore nuclear basket; nucleoplasm; nucleus; transcription export complex 2; nuclear pore; protein-containing complex
Genetic constraint (gnomAD): Loss-of-function variants: 112 observed, 170.37 expected, observed/expected ratio (o/e) 0.66, 90% interval 0.56 to 0.77. The upper end of that interval is the gene's LOEUF score, 0.77, which puts it in group 3 of 6, group 1 being the genes least tolerant of losing a copy. Missense variants: 2,374 observed, 2,456.5 expected, observed/expected ratio (o/e) 0.97, 90% interval 0.93 to 1. Synonymous variants: 962 observed, 974.57 expected, observed/expected ratio (o/e) 0.99, 90% interval 0.94 to 1.04.
Gene-disease validity (ClinGen):
ClinGen rates the evidence that MCM3AP causes each of these diseases.
peripheral neuropathy, autosomal recessive, with or without impaired intellectual development (autosomal recessive): Definitive.
Homologues: Orthologues: chimpanzee MCM3AP (99% identical), macaque MCM3AP (97% identical), dog MCM3AP (84% identical), rabbit MCM3AP (84% identical), guinea pig MCM3AP (81% identical), rat Mcm3ap (80% identical), pig MCM3AP (79% identical), mouse Mcm3ap (79% identical), tropical clawed frog mcm3ap (44% identical), zebrafish mcm3ap (41% identical), Caenorhabditis elegans mcm-3AP (15% identical). Paralogues in human: LENG8 (8% identical), SAC3D1 (6% identical).
Diseases named in the same sentence as MCM3AP in open-access papers:
MCM3AP is named in the same sentence as 41 diseases in open-access papers, as found by Europe PMC text mining. Sharing a sentence is not in itself a finding about the gene and the disease. The quoted sentences say what the papers report.
Intellectual disability (3 papers, 2019 to 2025). "Variants in MCM3AP were initially linked to intellectual disability in an affected sibling pair with progressive polyneuropathy and later with a complex phenotype with immunodeficiency, genomic instability, skin changes and myelodysplasia in a child." (PMID 32954258, 2019). "The retrospective study was conducted on 28 individuals with biallelic MCM3AP mutation-related diseases, including features such as mutations, motor development impairment, intellectual disability, weakness/atrophy, and cerebral magnetic resonance imaging abnormalities." (PMID 39228414, 2024). "Clinical clues to pinpoint the causative gene from the heterogeneous CMT2 and AR‐CMT2 group included pyramidal signs in SACS, MTRFR, and HSPB1, vocal cord paralysis in TRPV4, intellectual disability in MCM3AP, late disease onset in MME, in accordance with previous reports." (PMID 39776111, 2025). "Segregation of MCM3AP variants has previously been reported in patients with progressive polyneuropathy with or without intellectual disability." (PMID 32954258, 2019). "Variants in MCM3AP, encoding the germinal-centre associated nuclear protein, have been associated with progressive polyneuropathy with or without intellectual disability and ptosis in some cases, and with a complex phenotype with immunodeficiency, skin changes and myelodysplasia." (PMID 32954258, 2019).
Charcot-Marie-Tooth neuropathy (1 paper, 2019). "In this study, we report a novel variant in MCM3AP (p.Ile954Thr), in a family including three affected individuals with characteristic features of Charcot-Marie-Tooth neuropathy and multiple sclerosis, an inflammatory condition of the central nervous system without known genetic cause." (PMID 32954258, 2019).
developmental delay (1 paper, 2021). "However because patient ID5 only has a heterozygous DMXL2 variant, the developmental delay may also be due to other causes, such as variants in CCDC186 (MIM 619249; 10q25.3), ZRF2 or MCM3AP (MIM 603294; 21q22.3)." (PMID 33924653, 2021).
HCMV infection (1 paper, 2012). "In conclusion, we have identified the cellular factor MCM3AP as being essential for inhibition of cellular DNA synthesis by IE86 at IE times of HCMV infection in primary fibroblasts." (PMID 23094019, 2012). "On the basis that MCM3AP was initially suggested to be an MCM3 acetylation factor, we tested whether HCMV infection or over-expression of IE86 could lead to increased acetylation of MCM3." (PMID 23094019, 2012).
liver cancer (1 paper, 2019). An epithelial or non-epithelial malignant neoplasm that arises from the liver. "The role of long non-coding RNA (lncRNA) Minichromosome Maintenance Complex Component 3 Associated Protein (MCM3AP) Antisense RNA 1 (MCM3AP-AS1) has been analyzed in liver cancer." (PMID 31836002, 2019).
multiple sclerosis (1 paper, 2019). A progressive autoimmune disorder affecting the central nervous system resulting in demyelination. "Our data support further expansion of the clinical spectrum linked to MCM3AP variant and highlight that MCM3AP should be considered in patients with accompaniment of recessive motor axonal Charcot-Marie-Tooth neuropathy and multiple sclerosis." (PMID 32954258, 2019).
neuropathy (1 paper, 2024). A disorder affecting the nervous system that manifests with pain, tingling, numbness, and/or muscle weakness. "Overall, recessive mutations in MCM3AP are associated with neuropathy and ID as well as functional impairment of the GANP protein." (PMID 39228414, 2024).
virus infection (1 paper, 2012). "Finally, we confirmed that knock-down of MCM3AP could also affect the ability of virus to inhibit cellular DNA synthesis in the context of virus infection." (PMID 23094019, 2012).
tumor (4 papers, 2019 to 2021). "In this study, we systematically assessed the prognostic performance of DNA replication-related genes for predicting tumor recurrence and constructed a novel and robust signature including EREG, KCTD13, MCM3AP, MCM3, POLD2, TERF2, and TP73." (PMID 33748108, 2021).
infection (2 papers, 2012 to 2023). The state of being infected such as from the introduction of a foreign agent such as serum, vaccine, antigenic substance or organism. "Taken together these results support the view that the ability of IE86 to inhibit cellular DNA synthesis at IE times of infection is mediated by cellular MCM3AP and it occurs at a step later than licensing of cellular origins of replication." (PMID 23094019, 2012). "Our observations suggest that, at immediate early times of infection, IE86 prevents MCM function by recruitment of MCM3AP which prevents the pre-RC from initiating DNA synthesis." (PMID 23094019, 2012).
neurologic disorders (1 paper, 2024). "GANP protein depletion and/or loss of function impair the transcription and/or export of mRNAs, resulting in the distinct neurologic disease phenotypes associated with MCM3AP mutations." (PMID 39228414, 2024). "GANP, encoded by MCM3AP, is a protein associated with neurologic disorders in humans; defects in this protein have been described as causative agents of autosomal recessive Charcot–Marie–Tooth disease with ID." (PMID 39228414, 2024).
MCM3AP also shares sentences with these, for which no sentence is quoted: cancer (3 papers); lymphoma (3); hematological malignancies (2); peripheral neuropathies (2); Arts syndrome (1); Ataxia (1); bacterial infection (1); Cognitive impairment (1); congenital myopathies (1); cryptorchidism (1); development (1); Down syndrome (1); gastric cancer (1); Hodgkins lymphoma (1); Immunodeficiency (1); lymphoid neoplasm (1); mitochondrial disease (1); motor neuron degeneration (1); multiple acyl-CoA dehydrogenase deficiency (1); muscular dystrophies (1); Myelodysplasia (1); Obesity (1); ovarian carcinoma (1); polyneuropathy (1); ptosis (1); serous ovarian carcinomas (1); skin changes (1); tuberculosis (1); Vocal cord paralysis (1); X-linked disease (1).